S100A11 (S100 calcium binding protein A11)
Diseases named in the same sentence as S100A11 in open-access papers (continued):
Sharing a sentence is not in itself a finding about the gene and the disease.
liver fibrosis (5 papers, 2022 to 2025). "S100A11 has been shown to participate to myocardial and chemically-induced liver fibrosis through TGF-β dependent signaling pathways." (PMID 40841353, 2025). "By stimulating proinflammatory cascades by inflammatory gene expressing and profibrogenic cytokine releasing including Il1b, Tnf, Lgals3, S100a6, S100a4, S100a11, and S100a10, Mac1 was characterized as one of the profibrotic contributors during the liver fibrosis progression." (PMID 37724132, 2023). "Of interest here, the key role of extracellular S100A11 in hepatic fibrosis is highlighted by pharmacological evidence indicating that Tranilast, an inhibitor of S100A11 binding to RAGE, prevents not only liver inflammation in rats fed an MCD, but also fibrosis development." (PMID 36232334, 2022).
lymph node metastasis (5 papers, 2013 to 2023). "Moreover, several studies have shown that up-regulation of S100A11 is significantly associated with lymph node metastasis in patients with NSCLC." (PMID 32457792, 2020). "The results showed significantly higher S100A11 in patients with hematogenous metastasis than in patients with lymph node metastasis or without metastasis." (PMID 36860671, 2023). "High serum S100A11 levels in EOC patients were closely related to tumor pathological stage, postoperative residual foci, ascites volume, serum CA125 level, platinum-based chemotherapy response, and lymph node metastasis (P < 0.05)." (PMID 33763485, 2021).
melanoma (5 papers, 2021 to 2025). A malignant, usually aggressive tumor composed of atypical, neoplastic melanocytes. "Compared with those in the low-risk group, the melanoma patients in the high-risk group had high expression of S100A11 and CPC3 and low expression of PSME2, ARID5A, and SERPINE2 and had a shorter survival time." (PMID 35646893, 2022). "In addition, PSME2 and other four gene markers for malignant cells (ARID5A, SERPINE2, GPC3, and S100A11) were combined to develop a prognostic signature in melanoma." (PMID 36583022, 2022).
Sepsis (5 papers, 2012 to 2025). Sepsis is defined as life-threatening organ dysfunction caused by a dysregulated host response to infection. "The prognosis of sepsis patients was strongly linked to S100A11, QPCT, and IFITM2 based on meta-analysis and survival analysis(P < 0.05).GSEA analysis showed that S100A11, QPCT, and IFITM2 were significantly enriched in ribosome-related pathways." (PMID 39854580, 2025). "Among these, we found certain S100 family proteins (i.e. S100A12 and S100A11) exclusively elevated in sepsis samples, while traditional pro-inflammatory S100A8 and S100A9 were similarly expressed in both healthy and sepsis samples." (PMID 40965975, 2025). "The findings indicated a positive correlation between the survival of sepsis patients and the levels of S100A11, QPCT, and IFITM2 expression." (PMID 39854580, 2025). "The models of sepsis were constructed with different treatment groups, and S100a11 expression in the CLP group found to be higher than in the sham group, a change that was reversed by DCA." (PMID 38727856, 2024). "The CCR2 and S100A11 genes are up-regulated in early stages of sepsis in blood but down-regulated in the peritoneal cells in our sepsis model." (PMID 23009705, 2012). "In the sepsis group, the qPCR results showed that S100A11, QPCT, and IFITM2 expression levels were significantly higher in the sepsis group(P < 0.05)." (PMID 39854580, 2025). "Although this study provides preliminary evidence for S100A11, QPCT, and IFITM2 as potential biomarkers of sepsis, several limitations remain." (PMID 39854580, 2025). "In summary, this study provides preliminary evidence for S100A11, IFITM2, and QPCT as novel sepsis biomarkers." (PMID 39854580, 2025). "In this study, S100A11, QPCT, and IFITM2 were screened as new potential biomarkers for sepsis." (PMID 39854580, 2025). "This indicates that the control of S100A11, QPCT, and IFITM2 expression could be significant in the development of sepsis." (PMID 39854580, 2025). "The present study revealed the expression pattern, cell line localization, and functional enrichment of S100A11, IFITM2, and QPCT in macrophages, aiming at an in-depth exploration of the roles of S100A11, IFITM2, and QPCT in sepsis to evaluate their potential as novel biomarkers." (PMID 39854580, 2025). "The meta-analysis findings indicated variations in the levels of S100A11, QPTC, and IFITM2 expression among sepsis patients who survived and those who did not." (PMID 39854580, 2025).
asthma (4 papers, 2010 to 2025). "S100A11-gene derived circular RNA (circS100A11) is significantly higher in monocytes of pediatric asthma patients." (PMID 41164170, 2025). "Until now, S100A4, S100A8/S100A9 (calprotectin), S100A11, and S100A12 have been implicated in the pathophysiology of asthma, exhibiting both similarities and differences in their mechanisms of action." (PMID 41164170, 2025). "In contrast to the proteomic study of a chronic mouse asthma model that demonstrated marked down-regulation of S100A11, we observed an increased expression level of S100A11 during the EAR." (PMID 20691077, 2010). "However, an airway smooth muscle cell (ASMC) relaxing effect by S100A11 is also reported in an allergen-induced asthma model." (PMID 41164170, 2025). "In our studies, the increased expression levels of S100A8, S100A9, and S100A11 in asthma onset in rats were downregulated after acupuncture, which suggests that acupuncture had an effect on the regulation of inflammatory reactions in asthma." (PMID 23304218, 2012). "The role of S100A11 in promoting inflammation to ward off infections/allergens while also providing a compensatory relaxation effect in ASM cells underscores the complexity of S100 proteins in asthma and their potential as targets for nuanced therapeutic strategies." (PMID 41164170, 2025). "In the current study, a similar regulation of the expression of two S100 proteins, S100A8 (also known as calgranulin A, MRP8) and S100A11 (also known as calgizzarin, S100C), was observed in acupuncture-treated OVA-induced asthma onset rats." (PMID 23304218, 2012). "Our results indicate that acupuncture downregulates the expression of proinflammatory proteins (e.g., S100A8, RAGE, and S100A11) and upregulates the expression of anti-inflammatory proteins (e.g., CC10, ANXA5, and sRAGE) in the lung tissues of rats with asthma onset." (PMID 23304218, 2012).
lung adenocarcinoma (4 papers, 2015 to 2021). A carcinoma that arises from the lung and is characterized by the presence of malignant glandular epithelial cells. "S100A11 also called S100C or calgizzarin, overexpression is linked with alterations in K-RAS mutated lung adenocarcinomas as well as poorly differentiated lung adenocarcinomas." (PMID 34239729, 2021). "S100A11 protein was selectively expressed in NSCLC and displayed a particularly prominent effect in KRAS-mutated lung adenocarcinomas." (PMID 29607329, 2018). "In summary, the results of the present study suggested that the up-regulation of S100A11 played a role in tumor progression, particularly in KRAS-mutated lung adenocarcinomas." (PMID 26544866, 2015). "This suggests that TSN and S100A11 represent promising therapeutic targets to combat lung adenocarcinomas." (PMID 25940438, 2015). "Since the results obtained suggested that the up-regulation of S100A11 was involved in tumor progression, particularly in KRAS-mutated lung adenocarcinomas, its prognostic value was subsequently verified." (PMID 26544866, 2015). "Multiple linear regression analysis of relationships between S100A11 expression and clinicopathologic characteristics of stage I lung adenocarcinomas." (PMID 26544866, 2015). "The strong expression of S100A11 correlated with shorter disease-free survival in post-operative lung adenocarcinomas (p = 0.0182 in the Log-rank test)." (PMID 26544866, 2015). "Relationship between S100A11 expression and clinicopathologic characteristics of stage I lung adenocarcinomas." (PMID 26544866, 2015). "Significant upregulation of S100A11 protein, ranging from about a 1.3- up to an 8-fold increase in NSCLC species compared to the corresponding normal tissues was detected in 14 out of 17 pairs (82%) of lung adenocarcinomas and the adjacent normal tissues analyzed." (PMID 25940438, 2015).
mesothelioma (4 papers, 2016 to 2024). A usually malignant and aggressive neoplasm of the mesothelium which is often associated with exposure to asbestos. "Through this study, we hence strongly recognized a significant role of secreted S100A11 in mesothelioma progression." (PMID 29362358, 2018).
osteoarthritis (4 papers, 2017 to 2023). A noninflammatory degenerative joint disease occurring chiefly in older persons, characterized by degeneration of the articular cartilage, hypertrophy of bone at the margins and changes in the synovial membrane. "Increased S100A11 expression was recently demonstrated in human articular cartilage in patients with osteoarthritis (OA)." (PMID 28446208, 2017). "During the occurrence of osteoarthritis, CXCL8 (C-X-C Motif Chemokine Ligand 8) and TNF-α (Tumor necrosis factor α) can induce the expression of S100A11 and promote its release to the extracellular space to form a dimer." (PMID 34179021, 2021).
renal carcinoma (4 papers, 2009 to 2021). A carcinoma arising from the epithelium of the renal parenchyma or the renal pelvis. "On the contrary, S100A11 acts as a tumor suppressor in urinary bladder and renal carcinoma." (PMID 26106439, 2015).
adenoma (3 papers, 2016 to 2025). A neoplasm arising from the epithelium. "The knock-down of S100A11 seems to promote the occurrence of adenomas, but the number of lesions being analyzed was limited." (PMID 40841353, 2025). "A further significant increase in the mRNA for S100A11 was observed in the tissue of an advanced adenoma when compared to the healthy mucosa in those with an advanced adenomatous polyps." (PMID 33466593, 2021). "In the advanced adenoma group, differences between the healthy mucosa and adenomatous tissue were found in S100A6 (p = 0.002), S100A8 (p = 0.002), S100A9 (p = 0.021) and S100A11 (p = 0.029)." (PMID 33466593, 2021). "Differences in the mRNA for S100A4 in the non-advanced adenoma group and the mRNA for S100A9 and S100A11 in the advanced adenoma group between men and women were confirmed." (PMID 33466593, 2021).
diabetes (3 papers, 2020 to 2023). "The analysis confirmed that serum S100A11 levels were highly expressed in patients with impaired glucose tolerance, and similar results were seen in the livers of mice modeled with obesity, diabetes and high-fat diets." (PMID 36872321, 2023). "In our study, S100A11 expression increased as diabetes progressed, then whether it can be considered to play a role in the diabetic process, so we analyzed the relationship between S100A11 and related indicators in the glucose metabolic process." (PMID 36872321, 2023). "Lower expression in patients with diabetes was evident for SCPEP1, S100A11, LEP, PEBP1, SHGB, and APOF." (PMID 37792298, 2023). "Diabetes mellitus (DM) is a prevalent non-communicable metabolic disease, and S100A11 is a newly identified gene closely related to metabolism." (PMID 36872321, 2023). "However, comparable levels of PECAM1, CXCR2, SLC2A3, BST2, S100A11, S100A12, and CPNE3 were found in neutrophils from diabetes patients and controls (P > 0.05)." (PMID 32377527, 2020). "In addition, there were linear and nonlinear correlations between S100A11 and markers of glucose metabolism, demonstrating that S100A11 has a role in diabetes." (PMID 36872321, 2023).
intrahepatic cholangiocarcinoma (3 papers, 2021 to 2022). A carcinoma that arises from the intrahepatic bile duct epithelium in any site of the intrahepatic biliary tree. "Silencing of S100A11 in intrahepatic cholangiocarcinoma can reduce the level of SMAD2/3 phosphorylation which is induced by TGF-β1, and then inhibit cell migration, invasion and epithelial-mesenchymal transition (EMT)." (PMID 35752610, 2022). "In tumors with a high expression of S100A11, such as in intrahepatic cholangiocarcinoma, the silencing of S100A11 can inhibit TGF-β1-induced cell migration, invasion, and epithelial-mesenchymal transition (EMT)." (PMID 34179021, 2021). "Study has shown that S100A11 promotes epithelial mesenchymal transformation of intrahepatic cholangiocarcinoma induced by TGF-β1 through the Smad2/3 signaling pathway." (PMID 34663163, 2021).
psoriasis (3 papers, 2018 to 2024). An autoimmune condition characterized by red, well-delineated plaques with silvery scales that are usually on the extensor surfaces and scalp. "Following the decrease in Livin expression, a substantial reduction was observed in the levels of inflammatory mediators, namely, MMP‐7, Cath B, CXCL 6, S100A8, S100A7, and S100A11, which have crucial functions in psoriasis." (PMID 38332513, 2024). "Although the direct influence of S100A11 on psoriasis and AD remains unclear, S100A11 plays a role in suppressing cellular growth in human keratinocytes and is possibly involved in epidermal hyperplasia in these inflammatory diseases." (PMID 37891988, 2023).
thyroid cancer (3 papers, 2021 to 2024). "We have reported that S100A11 is highly expressed in various cancer tissues compared to those in normal tissues, whose relation is highly evident and consistent in the colon, small intestine, pancreas, bladder, and thyroid gland cancers." (PMID 38842658, 2024).
Arthritis (2 papers, 2011 to 2017). Inflammation of a joint. "In addition, S100A11 and several other S100 proteins are up-regulated in the early preclinical phase (before signs of arthritis are present) of adjuvant arthritis." (PMID 28446208, 2017).
endometrial carcinoma (2 papers, 2022). A malignant tumor arising from the epithelium that lines the cavity of the uterine body. "Although there have been studies linking S100A8, S100A11 as biomarker candidates for endometrial cancer detection, whether any other S100 gene family member is involved in endometrial carcinoma remains unclear." (PMID 35042454, 2022). "Interrogating Uterine Corpus Endometrial Carcinoma (TCGA-UCEC) and Uterine Carcinosarcoma (TCGA-UCS) cohorts revealed NCL to be the most highly upregulated gene in carcinosarcoma, with S100A11, LMNB2, RERG, E2F1 and CCNA2 representing key dysregulated NAGs in EC." (PMID 35682908, 2022).
Hepatitis (2 papers, 2021 to 2023). Inflammation of the liver. "Hepatocyte-derived lipotoxic EVs contain DAMPs and cell adhesion molecules such as S100a11 and ICAM1, which might affect immune cell responses, thus promoting liver inflammation in NASH." (PMID 34805145, 2021).
Impaired glucose tolerance (2 papers, 2022 to 2023). An abnormal resistance to glucose, i.e., a reduction in the ability to maintain glucose levels in the blood stream within normal limits following oral or intravenous administration of glucose. "Serum S100A11 levels were significantly higher in the impaired glucose tolerance and diabetic groups than in the normal glucose tolerance group (P < 0.01)." (PMID 36872321, 2023). "S100A11 expression is reduced during the treatment of impaired glucose tolerance, further reducing the prevalence of T2D." (PMID 36339449, 2022). "Serum S100A11 levels increased in patients with impaired glucose tolerance (IGT) of both genders." (PMID 36872321, 2023).
ischemia (2 papers, 2018 to 2020). A hypoperfusion of the BLOOD through an organ or tissue caused by a PATHOLOGIC CONSTRICTION or obstruction of its BLOOD VESSELS, or an absence of BLOOD CIRCULATION. "Moreover, Ad-S100A11 treatment improved the neurobehavioral function of the mice, including their performance on the Morris water maze test, the open field test and the rotarod test, at 7 days post ischemia." (PMID 29844306, 2018).
ischemic stroke (2 papers, 2018 to 2021). A stroke disorder caused by obstruction of blood flow to the brain, due to thrombotic (local blood clot formation) or embolic (due to a blood clot or other material traveling from another site) event. "In this study, we found that intracerebroventricular injection of the recombinant adenovirus vector Ad-S100A11 (carrying S100A11) strongly improved cognitive function and induced robust neuroprotective effects after ischemic stroke in vivo." (PMID 29844306, 2018). "In this study, we elucidated the effects of S100A11 on protecting against neuronal apoptosis induced by ANXA1 nuclear translocation after ischemic stroke." (PMID 29844306, 2018). "This study provides a novel mechanism whereby S100A11 protects against neuronal cells apoptosis, suggesting the potential for a previously unidentified treatment strategy in minimizing apoptosis after ischemic stroke." (PMID 29844306, 2018). "In a mouse model of ischemic stroke, S100A11 exerts neuroprotective effects, and upregulation of S100A11 protected against neuronal apoptosis by interaction with ANXA1 through the nuclear translocation signal (NTS) of ANXA1, thereby blocking ANXA1 nuclear translocation." (PMID 34179021, 2021).
liver diseases (2 papers, 2017 to 2025). "In the past years, S100A11 has been highlighted as one of the most promising targetable S100 proteins, with significant potential to mitigate liver disorders." (PMID 40841353, 2025). "In this context, we aimed to assess the therapeutic potential of targeting hepatocyte S100A10 and S100A11 in liver disorders." (PMID 40841353, 2025). "The different mouse models with various etiologies could collectively recapitulate the human disease and shed new light on the roles of S100A10 and S100A11 in liver diseases." (PMID 40841353, 2025). "Of these disease-associated proteins and proteins related to Galectin-3, NDRG1 showed a close relationship to carcinoma and liver diseases, and CD166, S100A11 and Galectin-1 were also related to carcinoma." (PMID 28701735, 2017).
medulloblastoma (2 papers, 2007 to 2020). A malignant, invasive embryonal neoplasm arising from the cerebellum. "The expressions of S100A1, S100A4, S100A10, and S100A11 are regulated by DNA methylation in medulloblastoma and may have potential impacts on the disorder of telencephalon in cerebral hernia." (PMID 32867218, 2020).
osteosarcoma (2 papers, 2023 to 2024). A usually aggressive malignant bone-forming mesenchymal neoplasm, predominantly affecting adolescents and young adults. "An earlier study using MVs from human osteosarcoma Saos-2 cells showed the presence of S100A4 and S100A6 but not S100A11." (PMID 36979349, 2023).